MSN (moesin)
Diseases named in the same sentence as MSN in open-access papers (continued):
Sharing a sentence is not in itself a finding about the gene and the disease.
cancer (continued). "We observed the selective packaging of P-gp, CD44, Ezrin, Radixin, and Moesin in MDR breast cancer derived MPs together with 117 other proteins unique to the resistance cargo, which we proposed may play a role in establishing the MDR phenotype in cancer cell populations." (PMID 29062386, 2017).
infection (14 papers, 2008 to 2024). The state of being infected such as from the introduction of a foreign agent such as serum, vaccine, antigenic substance or organism. "After infection, we detected EV markers such as Ezrin, Radixin and Moesin (ERMs), and other EV markers like Milk Fat Globule-EGF Factor 8 (MFG-E8, Lactadherin), but no contamination from other membrane compartments like the endoplasmic reticulum (CALNEXIN)." (PMID 36131943, 2022). "The expression of MSN was increased in NOX5-infected cells after 24 h of infection, and decreased after 48 h hours compared with GFP control cells." (PMID 36358519, 2022). "Moesin, vinculin, and actin cytoskeletons are host cell proteins which are disrupted during an infection via a diverse set of viral pathogens." (PMID 34696472, 2021). "Taken together, the down regulation of Ezrin, Radixin and Moesin with ∆potABCD suggest a novel mechanism by which pneumococci can escape host innate immunity and spread infection in the lung by regulating the expression of ERM complex." (PMID 27247105, 2016). "Recently, overexpression of Moesin was found to inhibit infection of both HIV and MLV viruses at a step prior to the initiation of reverse transcription." (PMID 18554410, 2008). "MSN is involved in cellular responses to stress by mediating the changes in cell shape, adhesion, and migration that occur under stress conditions, such as mechanical stress, inflammation, or infection." (PMID 38542474, 2024). "Intriguingly, siRNA knockdown of moesin resulted in enhanced infection." (PMID 22640593, 2012). "Notably, these hot sites or cell poles for infection are moesin/actin-driven pseudopods, where HIV-1 pore fusion formation and infection are favored." (PMID 37685911, 2023). "Therefore, moesin appears to be a key factor to be activated by HIV-1 to assure efficient and productive infection of the cell." (PMID 37685911, 2023). "Furthermore, stopping the activation signaling of moesin is sufficient to liberate the AFs from the cap, allowing HIV-1 capsid entry and infection." (PMID 37685911, 2023). "In the context of cytoskeleton dynamics, actin adaptors and enzymes that reorganize, stabilize and sever cortical F-actin, such as MSN (moesin), FLNA (filamin A), and GSN (gelsolin) have been involved in early infection, and are responsible for pore fusion and viral entry." (PMID 33995324, 2021). "Microglial actins in astrocyte-co-cultures were down-regulated after HIV-1/VSV infection and the proteins related to actin binding, polymerization and stability, including MARCKS, moesin, Wiskott-Aldrich syndrome protein (WAS) and gelsolin, were all up-regulated." (PMID 18575609, 2008). "Noteworthy, the interferon (IFN)-γ response differed significantly (p = 0.03) between WT and moesin-deficient mice at days 3 and 5 post-infection, yet higher serum IFN-γ concentration at day 5 post-infection did not impact the overall course of infection in moesin-deficient mice." (PMID 28560184, 2017). "Therefore, HIV-1 uses moesin and filamin-A to promote the aggregation of HIV-1 receptors in a pole of the cell, thereby regulating CD4/CXCR4-CCR5 diffusion at the cell surface in an actin cytoskeleton-dependent manner to facilitate the first events of the infection process." (PMID 37685911, 2023). "In addition, siRNA knockdown of moesin, but not ezrin, resulted in an inhibition of infection." (PMID 22640593, 2012). "Furthermore, ERM-proteins and the EWI-2-α-actinin complex association are linked to the infection process of other pathogens, such as HIV: while moesin supports HIV membrane fusion, EWI-2-α-actinin negatively regulates infection." (PMID 24553111, 2014).
neurodegenerative disease (2 papers, 2017 to 2023). A disorder of the central nervous system characterized by gradual and progressive loss of neural tissue and neurologic function. "These proteins included Septin, Ankyrin-2, and Moesin, which have been previously implicated and studied in relation to neurodegenerative diseases, including AD." (PMID 36937050, 2023). "Lastly, in cases where the present study evidenced down-regulated expression at the protein level (CDH4, MSN, BACE2) the next steps could involve the investigation of murine knock-outs against the background of neurodegenerative disease phenotypes." (PMID 28798667, 2017).
inflammation (1 paper, 2016). Aberrant reaction of the microcirculation characterized by movement of fluid and leukocytes from the blood into extravascular tissues. "Further, delivery of a Moesin phospho-null mutant into murine lung endothelium attenuated LPS-induced lung inflammation and vascular leak suggesting that MLCP opposes LPS-induced ALI by mediating the dephosphorylation of Moesin and Ezrin." (PMID 27976727, 2016).
intestinal diseases (1 paper, 2024). "Relevant proteins such as CALU, FLNA, MSN and HMGA2, which are related to intestinal diseases, were all upregulated in the IBD duodenal organoids." (PMID 38203746, 2024).
MSN also shares sentences with these, for which no sentence is quoted: Anxiety (2 papers); benign breast disease (2); endometrial Adenocarcinoma (2); prostatic adenocarcinoma (2); rhabdomyosarcoma (2); Sjögren syndrome (2); triple-negative breast carcinoma (2); abdominal aortic aneurysm (1); acquired aplastic anemia (1); antiphospholipid syndrome (1); asthma (1); bacterial infections (1); benign prostatic hyperplasia (1); Bladder Urothelial Carcinoma (1); brain tumors (1); carcinoma of the endometrium (1); cardiomyopathy (1); cerebral malaria (1); clear cell renal cell carcinoma (1); congenital stationary night blindness (1); cortical dysplasia (1); Cri-du-chat syndrome (1); cutaneous mastocytosis (1); Diabetes (1); ductal carcinomas (1); dyschezia (1); dysphoria (1); Dystonia (1); Epileptic encephalopathy (1); fibrosarcoma (1).
A further 29 diseases each share a sentence with MSN in 1 paper.